CCR2 (C-C motif chemokine receptor 2)
Diseases named in the same sentence as CCR2 in open-access papers (continued):
Sharing a sentence is not in itself a finding about the gene and the disease.
Stroke (continued). "Transcripts of chemokine receptors were also increased in the ischemic hemisphere of wildtype control mice, with a peak at 12 h for CCR1 and a peak at 7 d for CCR2, CCR5 and CX3CR1 after stroke." (PMID 23301011, 2013). "Though the main cytokines and chemokines revealed an attenuated expression in the sub-acute phase following stroke, chemokine receptors CCR1, CCR2 and CCR5 were found to be unaltered following TREM2 knockout." (PMID 23301011, 2013). "Several studies suggest a detrimental role for CCL2 in the progression of stroke injury, as both CCL2-/- and CCR2-/- mice exhibit reduced infarct volumes compared to wild-type controls." (PMID 22340958, 2012). "After the stroke, astrocytes can promote the migration and infiltration of monocytes from circulation, spleen, and bone marrow into the brain parenchyma, mainly through the CCL2/CCR2 axis." (PMID 40289984, 2025). "Stroke-induced cytokines (IL-6, TNF-α, and IL-1β) and MCP-1 and CCR2 mRNA levels were significantly higher in the diabetic brain compared to control at 1 day after MCAO, and this increased expression was sustained until 3 days post-stroke." (PMID 35784349, 2022). "In mouse and human brains, MCP-1 and its receptor (CCR2) are primarily expressed by microglia, and MCP-1/CCR2 signaling is involved in numerous neuroinflammatory diseases, such as multiple sclerosis, stroke, and Alzheimer’s disease (AD)." (PMID 33918634, 2021). "It has been known that the infarct area in stroke upregulatesseveral chemokines such as stromal-derived factor 1α (SDF-1α) and monocyte chemoattractant protein−1 (MCP-1) that canattract the migration of neuroblasts through their expression of correspondingreceptors CXR4 and CCR2." (PMID 35905716, 2022). "Our results confirmed that both CCR2 and CCL2 levels increased in brain parenchyma during acute phase after stroke, and that CCL2-overexpressing hUC-MSCs more effectively entered the brain parenchyma relative to naïve hUC-MSCs and distributed more densely around areas of upregulated CCR2." (PMID 33096826, 2020). "However, recent studies show that CCL2/CCR2 interaction positively affects functional recovery from stroke, and other studies confirm that CCL2 promotes the homing of CCR2-expressing stem cells from the bone marrow to the damaged brain, which contributes to brain repair following stroke." (PMID 33096826, 2020). "We confirmed that brain IL-6, IL-1β, TNF-α, CCR2, and MCP-1 expression levels were not significantly different between ND/veh and DD/STZ mice prior to stroke (data not shown)." (PMID 35784349, 2022). "Stroke induced an increase in MCP-1 at 6 h and 72 h after ischemia in the diabetic peritoneal cells, while IL-6, CCR2, and CD36 gene expressions were not different between the normal and diabetic cells." (PMID 24886035, 2014).
pulmonary fibrosis (51 papers, 2004 to 2025). Chronic progressive interstitial lung disorder characterized by the replacement of the lung tissue by connective tissue, leading to progressive dyspnea, respiratory failure, or right heart failure. "CCR2 has also been implicated in more frequent lung diseases of adulthood: Ccr2+ cells accumulate in experimental murine pulmonary fibrosis and have also been found enriched in human idiopathic pulmonary fibrosis." (PMID 40432300, 2025). "CCR2 deficient mice displayed decreased pulmonary fibrosis due to decreased infiltration of macrophages and expression of different macrophage specific metalloproteases during bleomycin and fluorescein isothiocyanate exposure." (PMID 37523510, 2023). "CCR2 signaling has been implicated in other lung diseases with interstitial involvement, including pulmonary fibrosis and pediatric interstitial lung disease." (PMID 33117383, 2020). "Further, Ccl-12 and Cxcr-4 that were both shown to be involved in pulmonary fibrosis, Ccl-3 which has been described to be important in systemic sclerosis, and Ccr-2 that is associated with allograft fibrosis, were overexpressed." (PMID 24143891, 2013). "CCL2 and/or CCR2 are implicated in the genesis and progression of diseases such as coronary artery disease, autoimmune disease, and pulmonary fibrosis." (PMID 17888174, 2007). "Specifically, increased levels of Tregs, CD16-CD56 positive NK cell phenotypes, and CCR2 positive monocytes are associated with a decreased risk of pulmonary fibrosis, potentially exerting protective effects by inhibiting inflammatory responses and promoting tissue repair." (PMID 38206731, 2023). "Previous findings of increased pulmonary fibrosis in CCR2-deficient mice compared to wild-type mice after treatment with Aspergillus conidia were accompanied by neutrophilic inflammation and the inability of CCR2-deficient mice to clear the organism normally." (PMID 15377395, 2004). "Previous studies showed that CCR2-deficient mice developed less pulmonary fibrosis in response to three different stimuli, including intratracheal bleomycin instillation, than did wild-type mice; however, those studies did not test the requirement for MCP-1 in the development of fibrosis." (PMID 15377395, 2004). "In addition, it has been shown that CCR2 deficiency in a mouse model of silica-induced pulmonary fibrosis resulted in an expansion of the fibrotic area, suggesting that CCR2hi monocyte-derived macrophages may have a suppressive role in fibrosis." (PMID 36949950, 2023). "The observation that deletion of CCR2 protected mice from BLM-induced lung fibrosis makes CCR2 a potential drug target." (PMID 41472725, 2025). "As CCL8 binds to CCR1 and CCR2, its effects involve the accumulation of CCR1+ inflammatory cells and CCR2+ macrophages and fibrocytes/fibroblasts, which contribute to collagen deposition, indicating a significant role in pulmonary fibrosis." (PMID 39768150, 2024). "In lung tissues that were explanted from pulmonary fibrosis patients, CCR2+ cells were observed to aggregate in perifibrotic niches and colocalize with increased radiotracer uptake." (PMID 38543082, 2024). "Ccr2-/- mice show reduced pulmonary fibrosis in response to bleomycin, with decreased myofibroblast differentiation, regulated macrophage infiltration and macrophage-derived MMP2 and MMP9 production, and lower fibrocyte mobilization." (PMID 39768150, 2024). "Gamma-herpesvirus infection up-regulates Ccl2 production and exacerbates pulmonary fibrosis in mice, with increased fibrocyte recruitment into the lungs in wild-type but abrogated in Ccr2-/- mice." (PMID 39768150, 2024). "In mouse models of lung fibrosis, Ccl7 is produced during both FITC- and bleomycin-induced fibrosis, and Ccr2 deficiency has been shown to protect against fibrosis." (PMID 39768150, 2024).
pulmonary fibrosis (continued). "Specifically, phenotypes such as Activated & resting Treg %CD4+, CCR2-positive monocytes, and CD16-CD56 positive NK cells were associated with a reduced risk of pulmonary fibrosis." (PMID 38206731, 2023). "Previous studies also demonstrated depletion of Ly6Chi circulating monocytes or alveolar macrophages, or knockout of the Ccr2 gene, all reduced pulmonary fibrosis in animal models." (PMID 37964270, 2023). "Previous studies have shown that depletion of circulating monocytes or CCR2 deficiency significantly reduces the degree of pulmonary fibrosis, suggesting that MoMs derived from classical monocytes may play a critical role in the development of pulmonary fibrosis." (PMID 36870972, 2023). "The elevated CCL2, CCL7, and CCR2 in the lung of the o-PF group suggest they are the important executors of pulmonary fibrosis in old rats, in addition to TGF-β." (PMID 36556326, 2022). "It has been demonstrated that CCR2 is important in the development of inflammation in lungs (asthma, tuberculosis and pulmonary fibrosis), liver, myocardium and others due to its importance in monocyte recruitment." (PMID 36361722, 2022). "One study suggested that CCR2+ monocytic myeloid-derived suppressor cells (M-MDSCs) inhibited collagen degradation and promoted lung fibrosis by producing TGF-β1." (PMID 35962397, 2022). "CCR2 expression and Mo-AMs have been shown to drive bleomycin-induced pulmonary fibrosis, raising the possibility that CCR2+ monocytes drive pulmonary fibrotic disease through differentiation into Mo-AMs." (PMID 36189800, 2022). "CCR2 signaling is critical for the initiation and progression of pulmonary fibrosis partly through the recruitment of pro-fibrotic bone marrow-derived monocytes." (PMID 34580234, 2021). "Recent studies showed that the CCL2/CCR2 axis has a vital role in the fibrotic formation in some diseases, including pulmonary fibrosis, renal fibrosis, and non-alcoholic liver fibrosis." (PMID 33614685, 2021). "Others have shown in the FITC model of lung fibrosis that CCL12/MCP-5 was deemed to be the active ligand for CCR2 involvement in the fibrotic response in vivo." (PMID 30764496, 2019). "CCR2-/- mice that have decreased amounts of CCL2 from anti-CCL2 gene therapy treatment are protected against bleomycin-induced pulmonary fibrosis." (PMID 24499286, 2014). "To explore more thoroughly the mechanisms through which pirfenidone ameliorates fibrocyte accumulation in the lungs of mice with BLM-induced pulmonary fibrosis, we investigated CCR2 expression on cultured fibrocytes." (PMID 24507087, 2014). "While expression of genes coding for soluble mediators (e.g. cytokines) were unchanged, receptors for several mediators known to participate in lung fibrosis were up-regulated (CCR2, FGFR2, FLT1, IGF1R, IL1R1 and IL6R)." (PMID 23844029, 2013). "Taken together, this highlights the potential for an anti-CCR2/CCL2 approach at inhibiting human lung fibrosis through attenuating fibroblast activity directly as well as reducing downstream fibrocyte profibrotic activities." (PMID 22011363, 2011). "A natural extension of these studies would be to assess and compare CCR2 on fibrocytes isolated from patients with IPF with those isolated during murine models of lung fibrosis." (PMID 22011363, 2011). "Inhibition of chemokine (C-C motif) receptor 2 (CCR2) during experimental models of lung fibrosis reduces lung collagen deposition, as well as reducing lung fibrocyte accumulation." (PMID 22011363, 2011). "Monocyte chemotactic protein 1 (MCP-1) promotes collagen synthesis and deletion of the MCP-1 receptor CCR2 protects from pulmonary fibrosis in ILD mouse models." (PMID 16095529, 2005). "In these models, the relevance of the MCP-1/CCR2 interaction was mainly addressed with respect to pulmonary fibrosis." (PMID 16095529, 2005). "Increased levels of Ccl12 may drive the Ccr2+ IFNγ-producing γδ T cell, reducing pulmonary fibrosis triggered by bleomycin in Ackr2-/- mice." (PMID 39768150, 2024).
pulmonary fibrosis (continued). "CCR2 signaling is therefore crucial for the development and progression of pulmonary fibrosis." (PMID 39850880, 2024). "Moreover, IL-10 induces fibrosis by fibrocyte recruitment and M2 macrophage activation dependent on the Ccl2/Ccr2 axis, with the abrogation of pulmonary fibrosis by treatment with anti-Ccl2 neutralizing antibodies in mice." (PMID 39768150, 2024). "Likewise, pre-treatment with a CCR2 antagonist reduced lung fibrosis in a mouse model of scleroderma." (PMID 38594676, 2024). "To this end, we imaged ECP-treated lung recipients using a PET-purposed radiotracer, 64Cu-DOTA-ECL1i, which specifically recognizes the extracellular loop number 1 of CCR2 and is under current clinical evaluation for noninvasive diagnosis of idiopathic pulmonary fibrosis." (PMID 36189800, 2022). "Similarly, Murine CCL12 (also known as MCP-5) is an analog of human CCL2, and CCL2 and its receptor CCR2 are one of the most widely studied chemokines and receptors in pulmonary fibrosis." (PMID 33176882, 2020). "CCR2 deficient mice, like CCL2 deficient mice, are unable to recruit monocytes to sites of inflammation, fail to clear certain intracellular pathogens and are protected from lung fibrosis." (PMID 17888174, 2007). "Thus, it is possible that the relative abundance or types of recruited cells in response to a particular airway challenge greatly influence the character or extent of lung fibrosis mediated by MCP-1 or CCR2.." (PMID 15377395, 2004). "In addition, polarized M1 macrophages may further activate through CCL/CCR2 axis, leading to excessive collagen deposition along with distorted lung tissue architecture, and ultimately resulting in pulmonary fibrosis and respiratory failure." (PMID 38273656, 2024). "In a mouse model of pulmonary fibrosis, Leucine-Rich Repeat Kinase 2 (LRRK2) expression is significantly reduced in alveolar type II epithelial (ATII) cells, and LRRK2-deficient ATII cells exhibit an enhanced ability to recruit profibrotic macrophages via the CCL2/CCR2 axis." (PMID 39850880, 2024). "CCR2+ CM also have the ability to differentiate into profibrotic AM that may drive lung fibrosis." (PMID 33621212, 2021). "In addition to the MCP-1/CCR2 axis, Th2 cytokines seem to mediate pulmonary fibrosis." (PMID 16095529, 2005). "Furthermore, CCR2-/- mice are protected from fluorescein (FITC) or bleomycin induced lung fibrosis." (PMID 16095529, 2005). "Specifically, certain immune cells like activated & resting Treg %CD4+, CCR2 on monocytes, and CD4 on CD45RA + CD4 + were identified as protective factors against pulmonary fibrosis (beta < 0)." (PMID 38206731, 2023). "For example, molecular imaging of C–C chemokine receptor 2 (CCR2) by 64Cu-DOTA-ECL1i detects monocyte recruitment in murine models of acute lung injury (ALI) and lung fibrosis and in patients with idiopathic pulmonary fibrosis (IPF)." (PMID 37273103, 2023). "CCR2 is the receptor of CCL2, CCL7, and CCL12, which plays an important role in the progression of pulmonary fibrosis." (PMID 36556326, 2022). "The expression of CCR2 by both cell populations, as well as the increase in the ligands IP-10 and MCP-1 in pulmonary fibrosis further highlights the role of inflammation in many end-stage lung diseases." (PMID 23915095, 2013). "Our result, in contrast to the reported requirement for CCR2 in the development of bleomycin-induced pulmonary fibrosis, suggests that different cell types and mediators may be operational in allergen-induced airway fibrosis than those observed in bleomycin-induced lung fibrosis." (PMID 15377395, 2004). "It has been shown that AT2 cell injury in a mouse model resulted in ‘C-C Motif Chemokine Receptor 2’ (CCR2)-mediated accumulation of non-resident CD11b+ macrophages and ‘lymphocyte antigen 6 family member C’ (Ly6C)hi monocytes, driving lung fibrosis." (PMID 40425299, 2025).
pulmonary fibrosis (continued). "The expression of CCL12 in lung tissue of pulmonary fibrosis mice is significantly increased, and CCR2−/−mice do not develop pulmonary fibrosis." (PMID 33176882, 2020). "IL-10 could induce lung fibrosis via promoting fibrocyte recruitment and M2 macrophage activation in a CCL2/CCR2 axis." (PMID 31105564, 2019). "Mice lacking CCL2 are protected from bleomycin-induced dermal fibrosis, while mice lacking the CCL2 receptor CCR2 are protected from bleomycin-induced lung fibrosis." (PMID 23845159, 2013). "Similar to MCP-1, percentages of CCR2+CD4+ cells were significantly higher in ILD children with pulmonary fibrosis as compared to children with non-fibrotic ILD." (PMID 16095529, 2005). "The accumulation of these nonresident cells and the development of pulmonary fibrosis in response to targeted alveolar injury is CCR2 dependent, thereby implicating ExM and Ly-6Chigh monocytes and the CCR2/CCR2-ligand axis as potential therapeutic targets to treat or prevent fibrotic lung disease." (PMID 30189872, 2018). "In addition, MCP-1 and CCR2+ T cells were also elevated in pediatric PAP that usually does not progress to pulmonary fibrosis." (PMID 16095529, 2005). "In conclusion, this study demonstrates that pulmonary inflammation, Th2 immune responses, Th2-mediated airway pathology, and lung fibrosis are remarkably intact despite the complete absence of MCP-1 or CCR2 in an Aspergillus antigen-driven model of allergic airway disease." (PMID 15377395, 2004). "Consequently, the role of MCP-1 and CCR2 in the development of allergen-induced lung fibrosis is not well established." (PMID 15377395, 2004). "Mechanistically, this reduction resulted from impaired CCR2 upregulation on monocytes in the absence of IRAK-M, consequently attenuating lung fibrosis development." (PMID 40650314, 2025). "Our children with pulmonary fibrosis had increased levels of MCP-1 and increased percentages of CCR2+ cells compared to children with non-fibrotic ILD." (PMID 16095529, 2005). "Children with lung fibrosis had significantly higher MCP-1 levels and CCR2+ T cells in bronchoalveolar lavage fluid compared to non-fibrotic children." (PMID 16095529, 2005).